CTLA4 (cytotoxic T-lymphocyte associated protein 4)
Diseases named in the same sentence as CTLA4 in open-access papers (continued):
Sharing a sentence is not in itself a finding about the gene and the disease.
tumor (continued). "Our data presented in the companion paper further demonstrate that anti-CTLA-4-induced tumor rejection requires Treg depletion but not blockade of the B7-CTLA-4 interaction." (PMID 29463898, 2018). "In two different tumor mouse models, the reduction of MDSC by a histone-deacetylase inhibitor, entinostat, in combination with antibodies against CTLA-4 and PD-1 led to 80% tumor eradication although the application of these ICI alone failed to induce anti-tumor effects." (PMID 29942309, 2018). "The human anti-CTLA4 antibody binds to CTLA4 on the T-cell surface, blocking CTLA4 from shutting down T-cell activation in the early stage, whereas the human anti-PD1 antibody binds to PD1, preventing tumor cells from inhibiting T-cell activity." (PMID 29311542, 2018). "Whereas neither anti-CTLA-4 antibody reduced Treg cell numbers in the spleen, both did in the tumor microenvironment, based on the percentile and absolute numbers of Treg cells." (PMID 29472691, 2018). "We also checked the percentage of demethylation across the eight patients and found that in PD-1 and CTLA-4, the percentage was increased consistently in tumor tissue of all patients but not in TIM-3." (PMID 29983831, 2018). "We did not observe any significant inhibition of tumor growth when they were treated with anti-PD-1 or anti-CTLA-4 alone." (PMID 30208943, 2018). "Absence of inhibitory tumor metabolism: high serum lactate dehydrogenase concentrations correlate with poor outcome to anti-CTLA-4 and anti-PD-1 antibody immunotherapy." (PMID 30200478, 2018). "Conversely, CTLA-4 inhibits the immune response at an earlier stage in the lymph nodes, and so CTLA-4 blockade results in a more widespread effect that is nonspecific for tumor antigens." (PMID 30497521, 2018). "Thus, CTLA-4 and IDO blockade combination significantly decreased tumor volume by 50% after 80 days, while during CTLA-4 blockade and imatinib administration alone tumors expanded by 40–60% over a similar period." (PMID 30191140, 2018). "CTLA-4 and PD-1 are frequently expressed on regulatory T-cells irrespective of PD-L1 tumor expression levels." (PMID 29644213, 2018). "Vaccine, anti-CTLA-4, or anti-PD-L1 alone or in combination independently with vaccination had modest effects on established tumor growth, while the combination of both anti-CTLA-4 and anti-PD-L1 without vaccination cured 60% of mice." (PMID 29377881, 2018). "When CTLA-4 was used alone without vaccination in the wild-type (WT) N2a model or the AgN2a model, only 40% and 0% of mice were cured of tumor, respectively." (PMID 29377881, 2018). "PD-LI or PD-L2 in tumor cells and CD80/86, which inhibits CTLA-4 and antigen-presenting cells, combine to maintain T cell activity, which can be divided into three types: PD-1, PD-L1, and CTLA-4." (PMID 30142174, 2018). "To characterize the phenotypes of the antigen-specific TILs, we focused first on data from tumour-bearing mice that did not undergo CTLA-4 blockade." (PMID 28916749, 2017). "Unlike CTLA4, which is induced in the initial T cell activation stage, PD-L1 is induced on tumour cells in response to inflammatory signals such as IFNs with respect to adaptive immune resistance." (PMID 28916815, 2017). "Anti-CTLA-4 works by promoting T cell responses that are largely non specific for tumors antigens, whereas the most important principle of anti-PD1 therapy is its localized effect (PD-L1 expression is mostly in tumor microenvironment)." (PMID 29195497, 2017). "It has been demonstrated that blockade of CTLA4 and PD1 could induce tumor regression and promote long-term survival in mouse glioma models." (PMID 28299344, 2017). "However, CD8 tumor-infiltrating cells showed significant expression of the inhibitory receptors PD1 and CTLA4." (PMID 28646041, 2017). "We provide preclinical evidence demonstrating that selumetinib does not significantly impair T-cell mediated anti-tumor activity in the presence or absence of anti-CTLA-4." (PMID 28807001, 2017).
tumor (continued). "While it has been previously published that anti-CTLA-4 or PD-1 monotherapy induces infiltration by TILs, this study suggests that CD8+ T cells infiltrating the tumor before therapy are particularly correlated with tumor response during therapy." (PMID 29088901, 2017). "The approval of anti-CTLA-4 monoclonal antibody (MAb), ipilimumab (MDX-010, Yervoy) from Bristol-Myers Squibb (New York, US), by US Food and Drug Administration (FDA) in 2011 has initiated a new era for tumor immunotherapy." (PMID 28978021, 2017). "Although CTLA-4 blockade alone did not alter tumor growth or survival, the combination of RT and checkpoint blockade delayed growth of the primary irradiated tumor, increased survival, and inhibited lung metastases formation." (PMID 28344743, 2017). "Hence, to increase the understanding of the natural course of NSCLC, further research on the roles of CTLA-4 expression in NSCLC, which can potentially guide treatment preferences and tumor sampling strategies, is needed." (PMID 28707078, 2017). "Injection of CTLA4-blocking Abs slowed down tumor growth compared with controls, but they were not as effective as PD1-blocking Abs (p < 0.03) or the combination of PD1 and CTLA4 blockade (p < 0.003)." (PMID 28646041, 2017). "Moreover, CD3+CD4+ T cells and CD3+CD8+ T cells derived from 4T1-tumor bearing mice expressed higher level of immunosuppressive markers including PD1, PDL1, LAG3, CTLA4 and TIM3 in peripheral blood and spleen than that in normal mice." (PMID 29383101, 2017). "For example, we found higher expression of Ctla4 and Lag3 in MLL-LNs that could inhibit anti-tumor immune responses." (PMID 29073272, 2017). "This review focuses on combination strategies of anti-CTLA-4, anti-PD1, and PD-L1 molecules with other coinhibitory molecules, costimulatory molecules, agents for molecules in tumor microenvironment, experimental cancer vaccines, cytotoxic chemotherapeutics, targeted agents, and radiation." (PMID 28848761, 2017). "Based on these findings obtained in blood and tumor, we hypothesized that CD137 critically impacted sensitivity to CTLA-4/PD-1 co-blockade in MMel." (PMID 28928380, 2017). "CTLA-4 blockade with one fraction of 12 Gy gave a statistically significant increase in survival times but not statistically significant primary tumor control compared to RT alone." (PMID 28344743, 2017). "Tumor-bearing mice were treated with MDSC depletion and CTLA-4 checkpoint blockade." (PMID 28915554, 2017). "The anti-tumor effects of [neratinib + valproate] exposure was amplified by a subsequent administration of an anti-PD-1 antibody but not by an anti-CTLA4 antibody." (PMID 29163826, 2017). "The expression of membranous PD-L1 on tumor cells, CD3+ and CD8+ tumor infiltrating lymphocytes (TILs), co-stimulatory (CD137, GITR, ICOS), and co-inhibitory immune checkpoint molecules (PD-1, CTLA-4, TIM-3) were assessed semi-quantitatively using immunohistochemistry." (PMID 28771603, 2017). "CTLA-4 expression in neither tumor epithelial cells (T-CTLA-4) nor stromal cells (S-CTLA-4) of primary tumors was significantly associated with disease-specific survival (DSS) in all patients." (PMID 28707078, 2017). "We observed an increased proportion of CTLA-4+ Ki-67high Tregs in the tumours of mice treated with IL-2WTFcnil but not with IL-2WTFc." (PMID 28497796, 2017). "However, as HIF1α is known to interact with CTLA-4 and its receptors, HIF-mediated blockade of CTLA-4 was shown to reduce the frequency of Tregs in the tumor." (PMID 28447025, 2017). "Among all epitopes tested, we were not able to identify novel antigen-specificities (>0.15%) both in tumours or in the peripheral circulation of anti-CTLA-4-treated mice that were not also seen in isotype mAb-treated mice." (PMID 28916749, 2017).
tumor (continued). "In here, Tregs expressing CTLA-4, ICOS, ENTPD1, CD45RA and PD-1 were the majority among tumoral Tregs and the so called effector Tregs, CD25hiFOXP3hiCD45RA- highly suppressive cells, were the most represented among tumor Tregs tissue derived." (PMID 29100374, 2017). "In line with our results in patients with LN+, recent studies in other carcinomas have reported that tumor CTLA-4 expression is a negative prognostic factor." (PMID 28707078, 2017). "However, when we combined anti-CTLA4 and anti-PD1 with Fas-Fc we observed a significant tumor growth inhibition (P = 0.0004, two-way ANOVA)." (PMID 29123081, 2017). "Combination of anti-CTLA-4 with selumetinib negated this up-regulation of Cox-2 and Arg1, reduced the frequency of CD11+ Ly6G+ myeloid cells, and led to the accumulation of differentiating monocytes at the Ly6C+ MHC+ intermediate state in the tumor." (PMID 28807001, 2017). "Indeed, circulating tumor-specific T cells in metastatic melanoma patients are functional although those isolated from tumor-draining LNs exhibit exhausted characteristics (decreased IFN-γ and increased CTLA-4 and LAG-3 expression)." (PMID 28220121, 2017). "In summary, the effect of combined administration of lycorine hydrochloride and anti-mouse CTLA-4 exhibited a potent therapeutic effect in the orthotopic and metastatic RCC tumor murine model and will serve as an excellent aid for developing a better treatment strategy for RCC." (PMID 28416753, 2017). "Neither tumor epithelial nor stromal CTLA-4 expression predicted DSS for all patients, or for pathological stage subgroups (data not shown)." (PMID 28707078, 2017). "Combination gMDSC depletion with CTLA-4 mAb checkpoint inhibition produced no delay in primary tumor growth or extension of survival in MOC2 tumor-bearing mice." (PMID 28915554, 2017). "CTLA-4 is overexpressed in activated CD4+T cell and CD8+T cell in tumor microenvironment." (PMID 28536525, 2017). "However, other markers for targeting tumor-infiltrated Tregs, such as OX40 and CTLA-4, are also available." (PMID 28537894, 2017). "Available data obtained in BC syngeneic mouse models showed that the RT-induced antitumor immunity required a combination with drugs able to counteract immunosuppressive factors (as CTLA4, TGF-β, and PD-1/PD-L1) to improve tumor control by radiation and definitively favor abscopal responses." (PMID 29163540, 2017). "Similarly, targeting PD-1, PD-L1, and CTLA-4 with monoclonal antibodies has been shown to reverse CD8+ T cell exhaustion and enhance lytic capabilities as well as promote tumor shrinkage and survival for many cancer patients." (PMID 29072624, 2017). "Despite the general success of checkpoint therapies, not all patients respond or achieve only partial tumor regression to anti-PD-1 or anti-CTLA-4 monotherapy." (PMID 27847783, 2016). "For the other groups of mice with surgical removal of primary tumours and treated with PLGA-ICG-R837 alone, anti-CTLA4 alone or even the combination of PLGA-ICG-R837 and anti-CTLA4, significant bioluminescence signals, indication of tumour metastases, also showed up, although at later stages." (PMID 27767031, 2016). "For example, treatments with cell based vaccines, transfer of effector T cells incorporating chimeric receptors or manipulations of immune checkpoint regulators including CTLA-4 and PD1 could be explored to induce tumor rejection using this model." (PMID 27171183, 2016). "We further confirmed the synergistic effects of combination therapy using a different murine tumour model, the RENCA model for RCC, where ∼70% of RENCA-bearing mice survived in combination therapy group and only 30% of or 0% of mice survived in α-CTLA-4 or α-PD-1 monotherapy group, respectively." (PMID 27498556, 2016). "Importantly, therapeutic blockade of CTLA-4, PD1 or TIM3 reverses T cell exhaustion, improves anti-tumor T cell responses, diminishes tumor size, and increases survival." (PMID 26967901, 2016).
tumor (continued). "Our results revealed that treatment with CTLA-4 blockade augmented the number of ICOS+ CD4+ T cells but not ICOS+ CD8+ T cells in the tumor, blood, and spleen." (PMID 26961085, 2016). "Analysis of CD8 T cells revealed that in the tumor/lungs ICOS expression showed the highest increases in MVA-BN-HER2-treated mice irrespective of CTLA-4 treatment." (PMID 26961085, 2016). "Recently, a challenging strategy of using antibodies to block the CTLA-4 molecule has emerged, and several studies have demonstrated the effects of CTLA-4 blockade on the induction of tumor immunity and the rejection of tumors not only in animal models but also in human patients." (PMID 26901565, 2016). "They found that CTLA-4 antibody, but not PD-1/PD-L1 blockade, synergized therapeutically with the PARPi, resulting in immune-mediated tumor clearance and long-term survival in a majority of animals (P < 0.0001)." (PMID 27634150, 2016). "IL-2 or α-PD-1/α-CTLA-4 treatment did not enhance the anti-tumor effect of SBRT (mean TDT of 40.7 (p = 0.71) and 36.8 days (p = 0.60), respectively)." (PMID 27160390, 2016). "However, the IR tumours also had high expression of the negative regulators of immune response PDCD1 (PD-1), CD274 (PD-L1) and CTLA4 (CTLA-4)." (PMID 26729235, 2016). "Similar strategies could also be used to target immune-checkpoint blockade aptamers (CTLA4, PD1, TIM3, etc.)to the tumor in order to reduce undesirable immune reactions in other tissues as well." (PMID 27783034, 2016). "Although blockade of CTLA-4 delayed tumor growth in our model, we did not observe an increase in T cell infiltration into MC-38 tumor." (PMID 27050669, 2016). "The reduction in the tumour was at least 10-fold for FOXP3+ and 4-fold for CTLA-4+." (PMID 27777963, 2016). "At day 35, when most of tumors of non-irradiated mice had grown out, there was a statistically significant difference in tumor size between mice that received SBRT and mice that received SBRT + IL-2, SBRT + α-CTLA-4/α-CD137, SBRT + α-PD-1/α-CD137 or SBRT + α-CD137." (PMID 27160390, 2016). "Unlike CTLA-4, PD-1/PD-L1 engagement does not interfere with co-stimulation but negatively regulates anti-tumor immunity through apoptosis and inhibition of T cell signaling." (PMID 28031817, 2016). "Using anti-CTLA-4 as a mIgG2b isotype, a partial reduction of Tregs at the tumor site was observed in MC38 and CT26 tumors in mice treated with both anti-CTLA-4 and anti-PD-1, and was accompanied by the expansion of tumor-infiltrating CD8+ T cells." (PMID 27610613, 2016). "In addition, more than half of the mice treated with the combination therapy (57 %) were still alive 100 days after tumor challenge, compared to 14 % of mice treated with MVA-BN-HER2 alone or 8 % of mice treated with anti-CTLA-4 alone." (PMID 26961085, 2016). "In the EL4 mouse thymoma model, it has been reported that neither DC-vaccination nor anti-CTLA-4 therapy alone is able to influence tumor growth, whereas combined therapy induced effective tumor rejection or growth inhibition." (PMID 27827885, 2016). "The current study demonstrates significantly decreased expression of PD-1 and CTLA-4 on tumor-infiltrating CD8+ T cells and decreased expression of their ligands (PD-L1 and CD86, respectively) on dissociated tumor cells from animals maintained on the KD when compared to control animals." (PMID 27178315, 2016). "The mean tumor size of mice pretreated with anti-CTLA4 versus control mice was not significantly different at the time of radiation therapy." (PMID 27281029, 2016). "IRAEs are due to non-specific blockade of CTLA-4 in self-targeted T cells that destroy healthy tissues and are not dissociable from the beneficial anti-tumor effect." (PMID 26110267, 2015). "Kaplan-Meier analysis was used to examine the relationships between CTLA4 SNPs and tumor; no statistical differences for rs733618, rs4553808, rs5742909, or rs3087243 existed between tumor and nontumor recipients." (PMID 25667935, 2015).
tumor (continued). "ISDN treatment alone did not have any effect on tumour outgrowth, but in combination with anti-CTLA-4 it very significantly improved the cure rate from 10% to 80%, displaying a clear synergistic effect." (PMID 26193793, 2015). "MSI colorectal cancers (CRCs) comprise approximately 15 % of the total sporadic CRCs, and these tumors have been shown to upregulate expression of immune checkpoints including PD-1, PD-L1, CTLA-4, LAG-3, and IDO in tumor infiltrating lymphocytes (TILs), stroma or tumor invasive front compartments." (PMID 26174086, 2015). "In addition, although two-thirds of CD8+ tumor infiltrating lymphocytes (TIL) express PD-1, one-third to half of CD8+ TIL are PD-1/CTLA-4 double-positive that exhibit more severe dysfunction than single-positive (PD-1+) TIL." (PMID 25851535, 2015). "Anti-CTLA-4 (Ipilimumab; Yervoy) and Anti-PD-1 (Nivolumab; Option and Pembrolizumab; Keytruda) monoclonal antibodies have been approved by the US FDA for melanoma (a type of skin cancer) treatment and are been currently tested in various tumor types." (PMID 26153774, 2015). "Since PD-1 blockade can indirectly impact CAR-T cell function (e.g., by reducing the prevalence of myeloid derived suppressor cells in the tumor microenvironment), co-administration of CAR-T cell therapy with CTLA-4 or PD-1 blockade remains an intriguing therapeutic option." (PMID 25990251, 2015). "In our study, the frequency of CTLA4 haplotype TACAG, which includes the rs231775A allele, was significantly higher in the tumor group (17.07%) than in the nontumor group (1.53%) (P = 0.0000)." (PMID 25667935, 2015). "Down-regulation of CTLA-4 significantly increased the in vivo anti-tumor effect of 19z1-CD80+ T cells but not that of 19-28z+ T cells." (PMID 26110267, 2015). "The tumor non-specific mechanism of CTLA-4 blockade, however, manifests as dose-limiting toxicity in many patients." (PMID 26082780, 2015). "However, administering anti-CTLA-4 with VSV established superior therapy and protected mice from tumor re-challenge." (PMID 26580645, 2015). "Indeed, by inhibiting CTLA-4 in 19z1-CD80+ T cells in which the CD28 signal comes from endogenous CD28 receptors activated by CD80 ligation, we almost reached the anti-tumor capacity of 19-28z+ T cells, in which CD28 costimulation is provided trough the CAR." (PMID 26110267, 2015). "The lack of significant anti-tumor activity in our patients from IL-2 or anti-CTLA-4 is not surprising in the absence of an effect on GVHD." (PMID 25806109, 2015). "Anti-CTLA-4 blockade also depleted intratumoral CTLA-4+ Treg cells by macrophages via ADCC in recent reports, which implies that CTLA-4 blockade can activate anti-tumor immunity in the presence of enough tumor-infiltrating lymphocytes (TILs)." (PMID 25893809, 2015). "Locally, delivery of IL12 to the tumor microenvironment promotes tumor regression in the B16 melanoma model, in the EL4 thymoma model, and in mouse models of glioblastoma in combination with CTLA4 blockade." (PMID 26082838, 2015). "In addition, the combination of anti-CTLA4, anti-TIM-3 and anti-LAG-3 produced further suppression of B16F10 tumor growth." (PMID 25614821, 2015). "They note that response to therapy was associated with T-helper type 1 gene expression, CTLA4 expression, and the absence of CX3CL1 in baseline tumor specimens." (PMID 26709361, 2015). "The set of major determinants of tumor immunogenicity in CRC we identified included not only immunosuppressive cells and chemokine receptors but also molecules which are currently tested in clinical trials: B7-2 (ligand of CTLA4) and PD-L2 (ligand of PD-1)." (PMID 25853550, 2015). "In order to determine if eradication of tumors in combination α-CTLA-4 and α-PD-L1 mAb treated mice resulted in sterilizing anti-tumor immunity, we next evaluated if the α-CTLA-4/α-PD-L1 mAb treated mice were protected against subsequent tumor inoculation." (PMID 25992292, 2015).